PVT1 (Pvt1 oncogene)
Diseases named in the same sentence as PVT1 in open-access papers (continued):
Sharing a sentence is not in itself a finding about the gene and the disease.
breast cancer (continued). "Odd ratio and its 95% confidence intervals were applied to evaluate the relationship between PVT1 and clinicopathological characteristics of breast cancer patients." (PMID 33663093, 2021). "In the univariate analysis, serum levels of PVT1, HOTAIR, PAI-1, and OPN were found to be significant predictors associated with breast cancer risk." (PMID 33670447, 2021). "Further, downregulation of p21WAF1/CIP1 promoted EMT, enhanced the cell viability and migration potential in response to long non-coding RNA plasmacytoma variant translocation 1 (PVT1) in distinct MDA-MB-231, MDA-BA-468 breast cancer cell lines." (PMID 33920506, 2021). "Similar to breast cancer, formation of PVT1 fusion proteins as a result of translocations occurring in intron 1 of the gene is also evident in numerous other cancers." (PMID 33499210, 2021). "PVT1 stabilizes MYC protein to promote tumorigenesis, and the PVT1 locus is often amplified in breast cancer." (PMID 34316694, 2021). "The serum level of PVT1 was significantly higher in breast cancer patients than in the controls, while that of NEAT1 was significantly lower in breast cancer patients compared to controls and fibroadenoma patients." (PMID 33670447, 2021). "In the present study, the serum expression of PVT1 was significantly increased in the breast cancer patients compared to the control subjects." (PMID 33670447, 2021). "Since then, recurrent intra-chromosomal inversions within intron 1 of PVT1 have been identified in breast cancer patients." (PMID 33499210, 2021). "Power analysis was carried out to assess the diagnostic value of PVT1, HOTAIR, NEAT1, MALAT1, PAI-1, and OPN in breast cancer." (PMID 33670447, 2021). "PVT1 was reported to enhance cell proliferation and inhibit apoptosis in ovarian and breast cancer cell lines and act as a regulator of chemosensitivity in pancreatic cancer." (PMID 33670447, 2021). "In this study, we analyzed the serum expression levels of lncRNAs PVT1, HOTAIR, NEAT1, and MALAT1, and their associated proteins, PAI-1, and OPN, in breast cancer patients compared to fibroadenoma patients and healthy subjects." (PMID 33670447, 2021). "Taken together, the result of this study indicates that PVT1 functions as an oncogene in breast cancer." (PMID 34922601, 2021). "For example, in a breast cancer model, gain of both PVT1 and MYC resulted in an increased proliferation of cells which was not evident by increase in PVT1 and MYC alone." (PMID 33499210, 2021). "Serum levels of PVT1, HOTAIR, PAI-1, and OPN were found to have diagnostic powers of 98%, 90%, 80%, and 88% in discriminating breast cancer from the healthy control." (PMID 33670447, 2021). "The overexpression of PVT1 was found to be correlated with several types of cancer such as acute myeloid leukemia, Hodgkin lymphoma, breast cancer, ovarian cancer, and pediatric malignant astrocytomas." (PMID 33670447, 2021). "The significance of serum PVT1, HOTAIR, NEAT1, MALAT1, PAI-1, and OPN levels as potential diagnostic biomarkers for breast cancer was assessed using a ROC curve." (PMID 33670447, 2021). "In previous studies, ovarian carcinoma, pancreatic carcinoma, breast carcinoma, etc. highly expressed PVT1." (PMID 34335862, 2021). "For example, upregulation of SOX2 activated PVT1 expression and accelerated the progression of breast cancer." (PMID 32549756, 2020). "The genomic amplification, rearrangements, and increased PVT1 expression exhibited oncogenic and epigenetic regulation effects on breast cancer, prostate cancer, and acute myeloid leukemia." (PMID 33329315, 2020). "On the contrary, a positive correlation in expression was observed between PVT1 and miR-1207-5p in breast cancer cells, with the overexpression of both promoting cell proliferation of breast cancer cells." (PMID 32117705, 2020). "For example, in breast cancer cells, the percentage of breast cancer cells at G2 phase increased after transfection with the PVT1-derived miR-1207-5p mimic compared with the control." (PMID 32117705, 2020).
breast cancer (continued). "Extra copies of the MYC gene along with extra copies of Pvt1, Ccdc26, and Gsdmc (all located in the 8q24.21 chromosomal region) were shown to be necessary for the formation of mammary tumors." (PMID 32117705, 2020). "For breast cancer, lncRNA Pvt1, which was ranked in top 5%, was validated to regulate triple-negative breast cancer through KLF5/beta-catenin signalling." (PMID 31787106, 2019). "Howard Chang’s group recently showed that targeted CRISPR interference at the PVT1 promoter enhanced breast cancer cell competition and growth in vivo due to the competition between PVT1 and MYC for engagement with four intragenic enhancers in the PVT1 locus." (PMID 31127282, 2019). "Elevated expression of SOX2 was reported to activate expression of the lncRNA PVT1, leading to breast cancer tumorigenesis." (PMID 31462898, 2019). "Among the most amplified genes, we find the oncogenes SOX2, EGFR, and MDM2, and also a noncoding gene, PVT1, the most amplified gene in breast cancer, with proven but as-of-yet uncharacterized proto-oncogenic effects." (PMID 31379928, 2019). "For example, SOX2 activated lncRNA ANRIL and PVT1 by binding their promoters in nasopharyngeal carcinoma and breast cancer, respectively." (PMID 30108202, 2018). "The genes located adjacent to the gene desert, MYC and PVT1 at one side and FAM84B at the other side, are candidates to play a role in 8q24 variant-mediated breast cancer susceptibility." (PMID 30526553, 2018). "Another previous study demonstrated that the upregulation of SOX2-activated LncRNA PVT1 expression promotes breast cancer cell growth and invasion." (PMID 29463902, 2018). "Despite its up-regulation in breast cancer tissues, mimicked by the miR-200 family members, PVT1 stopped working as ceRNA in the cancerous state." (PMID 30200360, 2018). "For example, in breast cancer, PVT1 is significantly upregulated, and directly interacts with SOX2 to drive EMT." (PMID 29701689, 2018). "We demonstrated that the drivers showed significant attributes of cancer genes, and significantly overlapped with known cancer genes, including MYC, CCND1 and ERBB2 in breast cancer, and the lncRNA PVT1 in multiple cancer types." (PMID 28719033, 2017). "Despite its up-regulation in breast cancer tissues, mimicked by the miR-200 family members, PVT1 stops working as ceRNA in the cancerous state." (PMID 28187158, 2017). "In particular, we focused on the withdrawal in breast cancer tissues of the PVT1 ceRNA activity and performed a gene expression and sequence analysis of its multiple isoforms." (PMID 28187158, 2017). "STAT6 was found to be a novel target of PVT1-derived miR-1207-5p, and miR-1207-5p promoted breast cancer cell growth by targeting STAT6, which in turn control CDKN1A and CDKN1B, confirming the tumor suppressing role of STAT6 in breast cancer." (PMID 28422733, 2017). "It was shown that patients had lower five years survival rate in breast cancer with alteration in PVT1 and SNHG6." (PMID 28938549, 2017). "Upregulation of SOX2 can activate PVT1 expression in breast cancer cells via binding to its promoter and promote breast cancer cell growth and invasion." (PMID 29244840, 2017). "Studies have suggested that overexpression of PVT1 induced the breast cancer invasiveness, lymph node metastasis." (PMID 28938549, 2017). "The mechanism for human PVT1 function, as shown in breast cancer, involves PVT1 stabilization of the MYC protein." (PMID 28875933, 2017). "In this study, we selected four lncRNAs which had expression alterations ranging from 12% to 20% in breast carcinoma, including PVT1, linc00467, SNHG6, linc00657." (PMID 28938549, 2017). "Confirming the cell-type specificity, levels of these markers of active chromatin were low in MCF-7 breast cancer cells that lack both HIF-α binding at the SNP-associated site and regulation of MYC or PVT1 RNA by hypoxia." (PMID 27774982, 2016).
breast cancer (continued). "PVT1 has been shown to bind and stabilize the Myc protein by preventing its phosphorylation at threonine 58 to promote carcinogenesis in breast cancer cells." (PMID 27232880, 2016). "The most “loss” of crosstalks between PVT1-mRNAs in the subtype 1 of ESCC were mediated by miR-186, which was inconsistent with previous report in breast cancer." (PMID 27966444, 2016). "Overexpression of PVT1 is a powerful predictor of tumor progression and patient survival in colorectal, ovarian and breast cancers." (PMID 25624916, 2015). "PVT1 has been studied in a variety of physiological and pathological processes, such as diabetic nephropathy, colorectal cancer, ovarian and breast cancers." (PMID 25890171, 2015). "It has been demonstrated that PVT1 is overexpressed in ovarian and breast cancer cells and when this expression is inhibited by siRNAs, cell proliferation is decreased and apoptosis increased." (PMID 24886442, 2014). "PVT1 is a lncRNA that appears to be strongly conserved between mouse and human and amplification of its locus is one of the most frequent events in breast cancer." (PMID 25033876, 2014). "The amplification of this locus has been shown to contribute to the pathophysiology of ovarian and breast cancer, and over expression of PVT1 has been detected in a subset of cases of AML and in other myeloid malignancies." (PMID 21436996, 2011). "This region delimited from centromere to telomere by TRPS1 and PVT1 contains MYC, two colorectal cancer risk loci, rs16892766 (8q23.3) and rs6983267 (8q24.21), and one breast cancer risk locus rs13281615 (8q24.21)." (PMID 20932292, 2010). "Several regulatory PVT1 fusions have been identified in breast cancer." (PMID 38473871, 2024). "Additionally, PVT1 has been reported to control breast cancer-related gene expression by competitively binding to miR-145-5p." (PMID 39317938, 2024). "Moreover, the expression level of PVT1 is closely related to the lymph node metastasis of breast cancer patients (P < 0.05)." (PMID 36941464, 2023). "We attempt to explain the mechanism of PVT1’s role in breast cancer from different perspectives." (PMID 36941464, 2023). "Therefore, we attempt to explain the mechanism of PVT1’s role in breast cancer from different perspectives." (PMID 36941464, 2023). "Indicating that PVT1 can be used as a target for breast cancer metabolism targeted therapy." (PMID 36941464, 2023). "In vivo we used a xenograft model to study the effect of PVT1 on breast cancer." (PMID 36941464, 2023). "In breast cancer, the amplification of the 8q24 region leads to both a gain in the copy number of the PVT1 gene and the accumulation of genetic alterations at the level of the promoter region of PVT1, which abrogates its expression." (PMID 36901971, 2023). "Increased expression of LINC00473 in HNSCC; LINC00114, MINCR and PVT1 in NPC; Linc-RA1 in glioma; LINC00473and CYTOR in NSCLC; NEAT1 and LINC00958 in cervical cancer; H19 in cardiac cancer; LINC02582 in breast cancer; and TUG1 in bladder cancer were associated with radioresistance." (PMID 36323697, 2022). "We also found that PVT1 could significantly discriminate between breast cancer patients and control subjects, with a sensitivity of 62%, a specificity of 64%, and an AUC of 0.67." (PMID 33670447, 2021). "In addition, the incidence of breast cancer is also affected by PVT1 overexpression due to genomic abnormalities." (PMID 34490041, 2021). "PVT1 is significant upregulated in breast cancer patients’ plasma and cell lines." (PMID 34922601, 2021). "Several studies have shown the connection between PVT1 and different miRNAs in breast cancer." (PMID 34527584, 2021). "In conclusion, our data suggest that the serum levels of PVT1, HOTAIR, NEAT1, PAI-1, and OPN could serve as promising diagnostic biomarkers for breast cancer." (PMID 33670447, 2021). "In conclusion, our results revealed that serum PVT1, HOTAIR, NEAT1, PAI-1, and OPN could be promising molecular diagnostic markers for breast cancer." (PMID 33670447, 2021).
breast cancer (continued). "Plasmacytoma variant translocation 1 (PVT1) is a long noncoding RNA (lncRNA) that is transcribed from a gene located at the 8q24 chromosomal region and has been demonstrated to play an oncogenic role in multiple cancers including breast cancer." (PMID 33801373, 2021). "However, accumulating evidence supports the notion that PVT1 possesses oncogenic functions in various cancers, including those of the digestive system, breast cancer, cervical cancer, and prostate cancer." (PMID 34518442, 2021). "Therefore, we hope that this meta-analysis can provide more accurate and objective evidence for the relationship between PVT1 expression and prognosis in patients with breast cancer." (PMID 33663093, 2021). "PVT1 may act as an oncogene in breast cancer through binding miR-128-3p and UPF1 and represents a potential target for BC therapeutic development." (PMID 34922601, 2021). "Our findings highlight a notable link between serum PVT1 overexpression and breast cancer, lending support to the formerly reported correlation of MYC and PVT1 co-amplification with rapid breast cancer progression and poor clinical survival in postmenopausal women with HER2positive breast cancer." (PMID 33670447, 2021). "Many SVs may be observed around the PVT1 promoter region of breast cancer cells, including deletions, inversions, and duplications." (PMID 35011637, 2021). "It was originally found to be associated with ovarian and breast cancer progression and reduced survival, and its silencing by short interfering RNA (siRNA) led to reduced growth and increased apoptosis in cell lines with MYC and PVT1 gain/overexpression." (PMID 34940760, 2021). "PVT1 promotes breast cancer cell proliferation and metastasis both in vitro and in vivo." (PMID 34922601, 2021). "Finally, the presence of SVs in breast cancer samples impairs the PVT1 promoter’s tumor suppressor action." (PMID 35011637, 2021). "Additionally, the tumor promoting activity of PVT1 was confirmed to be partially dependent on the negatively regulation on p21 in breast cancer." (PMID 32117705, 2020). "Similarly, PVT1 has a very highly ranked enhancer cis-regulatory score, was also a CRISPRi hit in ENCODE breast cancer cell lines, and demonstrated to inhibit MYC expression in cis via promoter competition for common enhancer elements." (PMID 30767760, 2019). "Interestingly, in breast cancer cells, a tumor suppressor role was recently ascribed to the PVT1 promoter, which is proposed to act as a DNA boundary element that insulates MYC from its downstream enhancers." (PMID 31338324, 2019). "Indeed, PVT1 lncRNA has been proven to play an oncogenic function by protecting MYC protein from phosphorylation-mediated degradation in breast cancer." (PMID 31601234, 2019). "The data indicated that SNHG6 might be related to pathogenesis and early diagnosis of breast carcinoma, and PVT1 was likely to inhibit breast cancer aggressiveness." (PMID 28938549, 2017). "However, PVT1 was significantly downregulated in breast cancer tissues when multiple primary neoplasms were present." (PMID 28938549, 2017). "In addition, PVT1 expression was elevated in breast cancer tissues and the increase was related with the GG genotype of rs13281615." (PMID 28430593, 2017). "Several studies have demonstrated the important roles of PVT1 in breast cancer." (PMID 28152521, 2017). "FAL1 and PVT1 are amplified in ovarian and breast cancer, respectively." (PMID 28747406, 2017). "Amplification of PVT1 correlated with short survival duration of ovarian and breast cancer." (PMID 29108264, 2017). "PVT1 also mediates the oncogenic activity of Myc in colorectal cancer and breast cancer." (PMID 28404954, 2017). "In human breast cancer, Pvt1 has been proposed to act by stabilizing MYC protein." (PMID 28875933, 2017).
breast cancer (continued). "Specifically, PVT1 emerged as a putative ceRNA modulating the activity of all members of the miR-200 family on their target mRNAs, which are well-known to be drastically involved in breast cancer morphogenesis and development." (PMID 28187158, 2017). "It is speculated that PVT1 downregulation could result in decreased breast cancer cells migration, metastasis and proliferation in breast cancer combined with primary lung cancer." (PMID 28938549, 2017). "Interestingly, ten highly ranked statistically significant putative regSNVs (p < 1.0E-03) appeared close to genes previously shown to be oncogenic in breast cancer such as PVT1, IGF1R, and GREB1." (PMID 27964748, 2016). "For example, PVT1 was markedly overexpressed in colorectal, ovarian and breast cancers." (PMID 25624916, 2015). "Interestingly, recent studies suggested a role for PVT1 in the pathophysiology of breast cancer by virtue of PVT1-mediated inhibition of apoptosis and increasing of proliferation, when overexpressed." (PMID 25883951, 2015). "Interestingly, recent studies suggested a role for PVT1 in the pathophysiology of breast cancer by virtue of PVT1-mediated inhibition of apoptosis, when overexpressed." (PMID 25033876, 2014). "Interestingly, a previous study found that MYC promoter interactions with enhancers in the PVT1 locus could be enhanced by a distinct mechanism, inactivation of the PVT1 promoter, in breast cancer cells." (PMID 34911936, 2021). "Moreover, a four lncRNA signature including PVT1, MAPT-AS1, LINC00667 and LINC00938 could precisely divide breast cancer patients into high- and low-risk groups." (PMID 34094972, 2021). "In human (ER−) HER2+ breast cancer, the PVT1 intron 1, which is close to the PVT1 promoter, is abnormally prone to cleavage, which might result in the fusion of PVT1 with another gene on the same chromosome leading to an abnormal transcription process not regulated by the PVT1 promoter." (PMID 31309249, 2019). "Thus the expression of these molecules could be predicted through the measurement of PVT1 expression in breast cancer." (PMID 28938549, 2017). "In a recent study, chromosomal engineering in mice showed that copy number gains in the Myc gene promote tumorigenesis in mammary tumors only if the downstream sequence encompassing Pvt1, Ccdc26, and Gsdmc is also amplified, suggesting that GSDMC may play a role in tumor progression." (PMID 27835699, 2016). "Finally, computational analysis of PVT1 suggests that it may act via binding and sequestration of mir-200 family members in breast cancer tissue." (PMID 27232880, 2016). "Several lncRNAs have been identified as positive regulators of breast cancer cell proliferation, including DANCR, PVT1, CCAT1, KCNQ1OT1 and SPRY4-IT1." (PMID 39912983, 2025). "The data show an upregulation of breast cancer related genes in T1 and C1 relative to 10A, including LRATD2, PCAT1, CASC19, CASC8, POU5F1B, PVT1 and MYC on chromosome 8." (PMID 38076897, 2024). "Since the human genomic locus on chromosome 8 (8q24), including the PVT1 gene, has been shown to be amplified in human breast cancer and PVT1 itself has been reported to stabilize the MYC protein, PVT1 has been described as a potential oncogene." (PMID 37782337, 2024). "In HER2-positive breast cancer patients, the co-expression of c-MYC and PVT1 has been shown to play an important role in promoting tumor malignancy." (PMID 36624401, 2023). "To further assess the function of PVT1 in breast cancer, we established a MDA-MB-231 cell line with stably PVT1 gene silencing by lentivirus-mediated short hairpin RNA interference and tested the knockdown efficiency." (PMID 36941464, 2023). "Consistent with the findings in breast cancer that PVT1 promoter and enhancers engage in MYC regulation, our group recently reported that in PCa MYC-Pro distally interacts with PVT1 locus enhancers." (PMID 37828515, 2023).